NPC1L1 (NPC1 like intracellular cholesterol transporter 1)
Diseases named in the same sentence as NPC1L1 in open-access papers (continued):
Sharing a sentence is not in itself a finding about the gene and the disease.
tumor (20 papers, 2012 to 2026). "This pattern was consistent across RCC subtypes, showing that combining NPC1L1 expression with tumor stage helps to better identify high-risk patients." (PMID 39598242, 2024). "In a mouse model, treatment with ezetimibe, which is a NPC1L1 blocker in the gut, that is responsible for dietary cholesterol adsorption, was also associated with inhibition of tumour angiogenesis." (PMID 33617503, 2021). "In RCC, although NPC1L1 levels were expected to be lower in advanced stages due to its reduced expression in tumor tissues compared to normal tissues, it was unexpectedly found to increase in higher stages." (PMID 39598242, 2024). "This trend of reduced expression in tumor tissues was also observed in other organs, such as the liver and testis, while in contrast, NPC1L1 expression was higher in tumor tissues of the stomach and pancreas compared to their normal counterparts." (PMID 39598242, 2024). "The median expression levels of NPC1L1 were compared between normal and tumor tissues across multiple organs using GEPIA2, with a particular focus on the kidney." (PMID 39598242, 2024). "In ccRCC and pRCC, the majority of tumor samples showed lower NPC1L1 expression compared to their corresponding normal tissues, indicating a general downregulation in tumor tissues for these subtypes." (PMID 39598242, 2024). "This suggests that NPC1L1 plays an important role in supporting tumor metabolism and growth, further validating its significance in RCC progression." (PMID 39598242, 2024). "In the kidney, NPC1L1 expression decreased significantly from 0.48 in normal tissue to 0.08 in tumor tissue." (PMID 39598242, 2024). "For accurate verification, the relative expression of NPC1L1 was analyzed in paired normal and tumor tissues from patients with CRC." (PMID 34511128, 2021). "A previous study revealed an inverse correlation between NPC1L1 expression and pathological stage, tumor differentiation, and vascular invasion in HCC." (PMID 34511128, 2021). "This cell line also mostly mimicked downregulated small molecule transporters seen in tumours, e.g. NPC1L1, SLC25A15/20, SLC2A2, SLC1A1 and SLC7A2." (PMID 30176945, 2018). "The ratio of malignant/tumor in NPC1L1−/− mice was significantly lower than in wild-type 20 weeks after AOM-DSS treatment." (PMID 25881076, 2015). "On the contrary, NPC1L1 knockout decreased TGF-β precursor in tumor and increased it in adjacent colon." (PMID 25881076, 2015). "Additionally, in chRCC, NPC1L1 expression was predominantly lower in tumor tissues compared to normal tissues, with most samples showing negative values." (PMID 39598242, 2024). "As RCC progresses to later stages, increased cholesterol requirements may lead to NPC1L1 upregulation, supporting tumor progression and metastasis." (PMID 39598242, 2024). "The importance of NPC1L1 in tumor prognosis has been demonstrated in investigations in the interim." (PMID 36034854, 2022). "Finally, the analysis of the combination of NPC1L1 expression and tumor stage demonstrated that although tumor stage is a critical prognostic indicator, high NPC1L1 expression also significantly influences patient outcomes, providing additional prognostic value beyond traditional staging factors." (PMID 39598242, 2024). "Therefore, as the tumor spreads, NPC1L1 may support the metabolic flexibility needed for enhanced tumor aggressiveness and survival." (PMID 39598242, 2024). "In the present study, similar to HCC, significant downregulation of NPC1L1 RNA expression is observed in RCC overall, as well as in the subtypes ccRCC, pRCC, and chRCC, with tumor tissues consistently showing lower expression levels compared to normal tissues." (PMID 39598242, 2024). "Collectively, these results reveal that NPC1L1 is a crucial regulator of DTP state and a potentially rational target for tumor patients with MDR disease in the clinic." (PMID 35023619, 2022).
tumor (continued). "The expressions of NPC1L1 and NPC2 in HCC tumor tissues were often lower than those in peritumor tissues, according to the patterns of expression in tumor and peritumor tissues." (PMID 36034854, 2022). "Interestingly, NPC1L1 knockout dramatically increased active TGF-β and p-gp in tumor but dramatically decreased them in adjacent colon." (PMID 25881076, 2015). "Beyond our expectation, NPC1L1 knockout did not significantly change its expression either in adjacent colon or in tumor." (PMID 25881076, 2015). "Ezetimibe has no known target other than NPC1L1, and NPC1L1 is expressed only in the intestine and in hepatocytes (in humans), but not by tumor cells." (PMID 22279565, 2012). "Moreover, given the role of NPC1L1 as the target of ezetimibe, exploring the use of ezetimibe as an adjuvant therapy in RCC could be one potential approach to inhibiting tumor progression and metastasis." (PMID 39598242, 2024). "In the TCGA_LIHC cohort, 16 of 120 genes were downregulated in HCC tissue rather than in adjacent non-tumor tissue, and 9 of 16 genes, namely, ALDH8A1, C11orf96, CLYBL, EFNB3, ENG, NPC1L1, PIM3, SEC14L2, and SLC8A1, displayed a significant difference (p < 0.05)." (PMID 33352935, 2020).
cardiovascular disease (4 papers, 2018 to 2024). "Supporting a role of intestinal cholesterol absorption in adipose tissue and cardiovascular disease, ezetimibe treatment or Npc1l1 deficiency in mice on a high-fat diet, reduces body weight and adipogenesis." (PMID 29899496, 2018). "Previous studies established that HMGCR and NPC1L1 gene polymorphisms were associated with baseline LDL-C concentrations, and HMGCR inhibitors (statins) and NPC1L1 inhibitors (ezetimibe) can reduce LDL-C concentrations and the risk of cardiovascular disease." (PMID 37355634, 2023). "Further connecting cardiovascular disease to dysfunctional lipid metabolism is the intestinal cholesterol absorption-related protein, Niemann-Pick type C1-Like 1 (NPC1L1)." (PMID 29899496, 2018). "Previous 2x2 factorial MR studies have identified combination therapies primarily within cardiovascular disease between PCSK9 and CETP inhibition, NPC1L1 and HMGCR inhibition, and IL-6 and PCSK9/CETP/NPC1L1 inhibition." (PMID 38962682, 2024). "Previous 2×2 factorial MR studies have identified combination therapies primarily within cardiovascular disease for PCSK9 and CETP inhibition, NPC1L1 and HMGCR inhibition, and IL-6 and PCSK9/CETP/NPC1L1 inhibition." (PMID 37398493, 2023).
infection (4 papers, 2012 to 2024). The state of being infected such as from the introduction of a foreign agent such as serum, vaccine, antigenic substance or organism. "Given that NPC1L1 is described as the main target of ezetimibe in humans, the profile of gene transcription of NPC1L1 was estimated over infection kinetics (3–24 h p. i.)on T. gondii-, N. caninum- and B. besnoiti-infected BUVEC by qRT-PCR." (PMID 34024307, 2021). "To examine the effect of fomiroid A on NPC1L1-dependent cholesterol uptake, we used lentivirus-mediated infection to establish Caco2 cells stably expressing rNPC1L1 (Caco2/rNPC1L1)." (PMID 25551765, 2014). "Therefore, future mechanistic understanding regarding NPC1L1-mediated cell signaling pathways during SARS-CoV-2 entry would certainly generate novel targets to prevent new infection." (PMID 38672177, 2024). "The depletion of several major actors of lipoprotein or cholesterol metabolism, such as SR-BI, LDL-R, and NPC1L1, has led to the conclusion that they are involved in HCV entry and early steps of infection." (PMID 24278733, 2012). "In line, we were not able to demonstrate a consistent infection-driven induction of NPC1L1 mRNAs since these gene transcripts could hardly be detected in infected BUVEC or control cells even though intestinal control tissues gave good PCR signals." (PMID 34024307, 2021). "Consequently, no infection-driven effect on NPC1L1 gene transcription was assumed." (PMID 34024307, 2021). "However, infection-related data showed that neither T. gondii-, N. caninum- and B. besnoiti-infected BUVEC nor non-infected controls have a reliable amplification of NPC1L1 mRNAs." (PMID 34024307, 2021).
metabolic disease (2 papers, 2009 to 2019). A congenital disorder (due to inherited enzyme abnormality) or acquired (due to failure of a metabolically important organ) disorder resulting from an abnormal metabolic process. "In Chinese Bama miniature pigs, zygote co-injection of Cas9 mRNA and sgRNA (single guide RNA) was used to delete Npc1l1 (Niemann-Pick C1-Like 1), efficiently producing biallelic mutant pigs to study how Npc1l1 influences cardiovascular and metabolic diseases." (PMID 34691891, 2019).
digestive system cancer (1 paper, 2025). A primary or metastatic malignant neoplasm involving any part of the digestive system. "We comprehensively assessed the potential impact of genetic variants related to LDL mediated by HMGCR, PCSK9, and NPC1L1 on digestive system cancers." (PMID 40443776, 2025). "After constructing the genetic instruments, we discovered that the genetic variants associated with LDL mediated by HMGCR, PCSK9, and NPC1L1 have distinct effects on digestive system cancers, and these findings were validated through meta‐analysis across two independent GWAS datasets." (PMID 40443776, 2025).
NPC1L1 also shares sentences with these, for which no sentence is quoted: Hyperglycemia (3 papers); Nonalcoholic Fatty Liver Disease (3); coronary atherosclerosis (2); ischemic stroke (2); adenoma (1); Alzheimer disease (1); aneurysm (1); Anxiety (1); bladder cancer (1); bladder neck obstruction (1); cardiomyopathy (1); cervical cancer (1); Cholestatic liver disease (1); cognitive decline (1); Cognitive impairment (1); coronary artery calcification (1); dementia (1); Dengue virus infection (1); depression (1); diabetic neuropathy (1); dyslipidaemia (1); endocrine diseases (1); erectile dysfunction (1); fibrosis (1); head and neck squamous cell carcinoma (1); hemorrhagic thrombocythemia (1); Hypertension (1); inflammatory bowel disease (1); intermediate coronary syndrome (1); major depressive disorder (1).
A further 17 diseases each share a sentence with NPC1L1 in 1 paper.